UHRF1 (ubiquitin like with PHD and ring finger domains 1)
Diseases named in the same sentence as UHRF1 in open-access papers (continued):
Sharing a sentence is not in itself a finding about the gene and the disease.
cancer (continued). "During the recent years, UHRF1 has received great concerns as a novel diagnostic marker of cancer." (PMID 27431502, 2016). "Moreover, a recently published study has shown that UHRF1 depletion in cancer cells causes G2/M cell cycle arrest and apoptosis accompanied with phosphorylation of cyclin-dependent kinase 1 (CDK1) which is in agreement with our present data." (PMID 23688286, 2013). "Moreover, a recently published study has shown that depleting cancer cells of UHRF1 causes cell cycle arrest in G2/M and apoptosis." (PMID 22412883, 2012). "To determine whether the disruption of the Dnmt1/PCNA/UHRF1 interactions can promote the tumor transformation of Astro#40 and Ntv-a cells, we firstly investigated whether these cells acquired some hallmark of cancer after their transfection by the pUP plasmid." (PMID 20613874, 2010). "Our result indicates that an immunohistochemistry-based UHRF1 detection in urine sediment or surgical specimens can be a sensitive and cancer-specific diagnostic and/or prognosis method, and may greatly improve the current diagnosis based on cytology." (PMID 19491893, 2009). "Therefore, UHRF1 may be used as a diagnostic biomarker, as well as a potential target for the development of anti-cancer drugs." (PMID 38725075, 2024). "Notably, this study suggests that UHRF1 levels are associated with cancer immunity." (PMID 35656341, 2022). "Additionally, the expression of cancer stem cells-related genes was increased by UHRF1 deficiency." (PMID 28584306, 2017). "Therefore, we investigated whether UHRF1 deficiency also triggers changes in the numbers of cancer stem-like cells." (PMID 28584306, 2017). "In addition, UHRF1 was downregulated to a greater extent in CD133+ cells compared with CD133− cells, indicating that UHRF1 deficiency may contribute to the maintenance of cancer stem-like cells." (PMID 28584306, 2017). "If so, then UHRF1 could be an important diagnostic biomarker and prognostic indicator for cancer." (PMID 26884069, 2016). "Therefore, in our conclusion, an immunohistochemistry-based UHRF1 detection in urine sediment can be a sensitive and cancer-specific diagnostic method, and may greatly improve the current diagnosis based on cytology." (PMID 19491893, 2009). "We previously showed that UHRF1, a central regulator of DNA methylation, contributes to cancer progression; however, its function in IBD remains poorly understood." (PMID 41657307, 2026). "Overexpression of DNMT1 or recruitment of DNMTs by proteins such as UHRF1/2 can exacerbate hypermethylation-mediated silencing of genes that regulate cell cycle, apoptosis, and DNA repair, all of which are hallmarks of cancer." (PMID 40558829, 2025). "G9a and UHRF1 were significantly overexpressed in cancer compared to normal ducts (p < 0.001 for both), although DNMT1 was not significantly overexpressed in this comparison." (PMID 39810240, 2025). "Although cancer genomes often exhibit global hypomethylation, this occurs, paradoxically, alongside the frequent upregulation of DNA methyltransferase 1 (DNMT1) and its cofactor, UHRF1, in many cancers." (PMID 40558829, 2025). "The Cancer Cell Line Encyclopedia (CCLE) database was explored to elucidate the expression patterns of UHRF1 in different tumor cell lines." (PMID 40301374, 2025). "UHRF1 depletion results in significant promoter demethylation and gene upregulation in cancer cells." (PMID 40643491, 2025).
cancer (continued). "Studies have demonstrated that UHRF1 inhibits the reprogramming of cancer stem cells through epigenetic mechanisms, thereby suppressing HCC and ameliorating hepatocellular injury." (PMID 40243942, 2025). "UHRF1 is an epigenetic gene regulator that silences tumor suppressor genes by regulating DNA methylation in cancer cells." (PMID 41373864, 2025). "Nevertheless, the potential for an uncharacterized regulatory relationship, combined with extensive evidence implicating UHRF1 in tumorigenesis across multiple cancers, made UHRF1 a biologically compelling candidate for functional investigation in CCA." (PMID 41373864, 2025). "Numerous studies revealed that overexpression of UHRF1 was frequently found in various cancers and contributed to poor prognosis partly by promoting cell proliferation." (PMID 40490444, 2025). "Until now more than 726 or 431 publications have been posted in the Pubmed database when “UHRF1” or “UHRF1 and Cancer” was used as the subject word of search." (PMID 38725075, 2024). "For example, the hypomethylated and overexpressed gene UHRF1 has oncogenic functions promoting tumorigenesis through the silencing of DNA repair genes and inhibiting apoptosis in various cancers." (PMID 39189258, 2024). "Aberrant overexpression of UHRF1 has been reported in more than ten cancer types, indicating that UHRF1 is a typical oncogene, and plays a critical role in the cancer initiation and progression." (PMID 38725075, 2024). "The mechanisms underpinning the essentiality of UHRF1 and DNMT1 for long-term cancer cell proliferation have been suggested to be linked with their role in DNA methylation homeostasis." (PMID 38580649, 2024). "As research continues to expand our understanding of UHRF1 and its role in cancer, novel therapeutic strategies are likely to emerge." (PMID 39051184, 2024). "SET7/8 inhibitors have already been developed to treat cancer in the preclinical studies, since they exerts anti-tumor efficacy by destroying UHRF1 protein stability." (PMID 38725075, 2024). "In our research, we proposed a novel mechanism of YTHDF1 post‐transcriptionally regulated UHRF1 level that promotes cell proliferation and cancer metastasis while inhibiting cell apoptosis." (PMID 38683130, 2024). "Aberrant overexpression of UHRF1 is observed in a number of types of cancer, and the overexpression of UHRF1 suppresses the transcription of TSGs through DNMT1-mediated DNA methylation." (PMID 39267107, 2024). "A deep understanding of these crucial mechanisms of UHRF1 is pivotal for the development of novel UHRF1-targeted anti-cancer therapeutic strategies in the future." (PMID 38725075, 2024). "It has been reported that UHRF1 overexpression has been observed in various cancer types, and artificial overexpression of UHRF1 promotes tumorigenesis and cancer progression through DNA methylation." (PMID 38725075, 2024). "UHRF1 induces the ubiquitination of several tumor suppressor proteins, thereby is regarded as a potential anti-cancer drug target." (PMID 38725075, 2024). "We then use genomics and bioinformatics to precisely describe the DNA demethylation dynamics in these cells, leading to the conclusion that UHRF1 maintains DNA methylation in cancer cells not only by stimulating DNMT1." (PMID 38580649, 2024). "UHRF1 degradation inhibits the proliferation and migration of cancer cells, while also facilitate the process of senenscence." (PMID 38725075, 2024). "UHRF1 is a downstream effector of the RB/E2F pathway, which is nearly universally deregulated in cancer." (PMID 39051184, 2024). "UHRF1 is often overabundant in cancer cells, contributing to an environment conducive to uncontrolled proliferation." (PMID 39051184, 2024). "Collectively, these insights into UHRF1’s involvement across various cancers emphasize its central roles in modulating tumor growth, cell cycle dynamics, and epigenetic landscapes." (PMID 39051184, 2024).
cancer (continued). "UHRF1 plays a crucial role in cancer initiation, progression, metastasis and recurrence, and becomes an ideal drug target since UHRF1 knockdown inhibits tumor progression." (PMID 38725075, 2024). "To investigate the respective roles of DNMT1 and UHRF1 in cancer cells, we chose as a model the human colorectal cell lines HCT116 and DLD1, as they have been widely used to study the genetic and epigenetic events that cause and sustain transformation." (PMID 38580649, 2024). "Here the authors show that, beyond activating DNMT1, UHRF1 has crucial regulatory functions in cancer cells." (PMID 38580649, 2024). "Cumulative evidences suggest that UHRF1 and USP7 interact to form a complex, which in turn influences UHRF1 functions on chromatin remodeling, gene expression, and cellular differentiation, ultimately driving cancer development and progression." (PMID 38725075, 2024). "In sum, UHRF1’s pivotal role in cancer epigenetics propels it to the forefront of therapeutic targeting." (PMID 39051184, 2024). "A study revealed that targeting UHRF1 alone is insufficient to reactivate epigenetically silenced genes, which are often observed in cancer." (PMID 39051184, 2024). "UHRF1 has drawn considerable attention as a therapeutic target due to its significant role in cancer pathogenesis." (PMID 39051184, 2024). "With the aid of illustrations and tables, we comprehensively elucidated the roles of UHRF1 PTMs in cancer progression." (PMID 38725075, 2024). "The epigenetic reader UHRF1 is found to be an oncogene that is overexpressed in multiple human cancer cells." (PMID 39709438, 2024). "The UHRF1 gene is involved in chromatin regulation and acetylation, which produces a great impact on tumorigenesis and cancer progression." (PMID 39596491, 2024). "A large number of natural drugs antagonize the UHRF1 effects in vitro, but need to be improved in order to be employed for anti-cancer therapy." (PMID 37630248, 2023). "Small molecules that bind to the SRA domain can perturb the binding of UHRF1 with HM DNA and thus regulate the methylation levels in cancers." (PMID 37630248, 2023). "In HeLa and MCF-7 cancer cells, shikonin down-regulates UHRF1 expression and up-regulates the expression of p16INK4A and TP73." (PMID 37630248, 2023). "CDC7 inhibitors have been successfully administered to patients with solid tumors, whereas UHRF1 inhibitors require further studies to determine their application in cancer treatment." (PMID 36725843, 2023). "During DNA replication, UHRF1 accumulates at DSBs through its interaction with the BRCT (BRCA1 C-terminal) domain of BRCA1 (breast cancer gene 1) and phosphorylation of UHRF1 at Ser 674 by CDK2/cyclin." (PMID 37630248, 2023). "Although there have been several studies regarding UHRF1 in liver injury and cancer, most of the results were obtained from HCC cells in vitro." (PMID 37380646, 2023). "UHRF1 is frequently overexpressed in several types of cancers and plays an oncogenic role in cancer progression." (PMID 37380646, 2023). "It was reported that UHRF1 depletion remarkably decreased cell viability by elevating the expression of TSGs in several cancer types." (PMID 37788997, 2023). "The epigenetic integrator UHRF1 is overexpressed in nearly all cancer types, gaining the status of a potential oncogenic protein and being likely to become a universal biomarker for cancer." (PMID 37630248, 2023). "UHRF1 as a typical oncogene aberrantly overexpresses in a number of cancer types, and contributes to cancer initiation and progression." (PMID 37788997, 2023). "In the case of UHRF1, the problem of specificity can be addressed efficiently, as UHRF1 expression is up-regulated in a variety of cancers in comparison with normal cells." (PMID 37630248, 2023). "In summary, these results showed that UHRF1 silencing reduced cancer cell stemness by suppressing GLI1 expression." (PMID 37380646, 2023).
cancer (continued). "It was later observed that the UHRF1 levels peaked during the G1 and G2/M phases in normal cells, but were found to be consistently high in cancer cells." (PMID 37630248, 2023). "This higher sensitivity of cancer cells over normal cells was attributed to the higher expression of UHRF1 in cancer cells." (PMID 37630248, 2023). "Recently, the UHRF1/BRCA1 DNA repair complex was shown to constitute an interesting target to treat cancer as it sensitizes the cells to DNA damage by giving them less opportunity to initiate DNA repair." (PMID 37630248, 2023). "As a consequence, UHRF1 overexpression is involved in tumor proliferation, the inhibition of DNA repair, and the development of resistance toward anti-cancer therapy." (PMID 37630248, 2023). "In normal mouse testis a near complete co-localization of Uhrf1 and Ki67 was observed, while in the two cancer samples (KP mouse and human PDX) UHRF1 was also present in Ki67-negative non-dividing cells." (PMID 37407562, 2023). "Integrated RNA-seq and whole genome bisulfite sequencing revealed widespread hypomethylation induced by UHRF1 silencing epigenetically reprogrammed cancer cells toward differentiation and tumor suppression." (PMID 37380646, 2023). "Here we shown that in KRAS mutant cancer cells treatment with this inhibitor elicits an effect similar to that of UHRF1 genetic ablation." (PMID 37407562, 2023). "Uhrf1 immunostaining of tumor-bearing lungs of KP and UKP mice revealed the presence of Uhrf1 protein in all cancer lesions, suggesting incomplete Uhrf1 gene inactivation by the Cre recombinase in the UKP mice." (PMID 37407562, 2023). "A DMR harboring 22 CpGs, which were hypermethylated in carcinoma, was identified from the CpG shore region located in the second exon among 17 exons of the UHRF1 gene." (PMID 37460953, 2023). "On the contrary, UHRF1 downregulation via DNA demethylation and H2 acetylation inhibits cancer development, inducing re-expression of TSGs and promoting DNA repair inhibition." (PMID 36060265, 2022). "UHRF1 is highly expressed in proliferating and cancer cells, and it has been identified as a novel AMPK gate-keeper in cellular metabolism by interacting with AMPK and suppressing its activity." (PMID 35035504, 2022). "UHRF1 expression in epithelial tumors positively correlates with the stage, grade, drug resistance, and maintenance of cancer stem cell characteristics and has been suggested as a putative oncogene." (PMID 36077796, 2022). "At the same time, UHRF1 has received considerable attention as a promising biomarker and an important mediator of various human cancers." (PMID 35656341, 2022). "Ubiquitin-like with PHD and Ring Finger domains 1 (UHRF1) has been identified as a critical downstream effector of the RB/E2F signaling pathway that is overexpressed in various cancers." (PMID 36068209, 2022). "More and more studies have shown that UHRF1 plays a crucial role in the development of cancer, but the comprehensive analysis of UHRF1 in different cancers is still insufficient." (PMID 35656341, 2022). "Given the functional importance of UHRF1 during oncogenesis in multiple types of cancer, much effort has been devoted to identifying genetic targets of UHFR1." (PMID 35664070, 2022). "In conclusion, this study elucidates the close correlation and prognostic significance of UHRF1 expression in various human cancer pathogenesis." (PMID 35656341, 2022). "Altogether these compounds appear to be potential UHRF1 inhibitors and anti-cancer drugs but their mechanisms of action need to be further investigated." (PMID 36060265, 2022). "High levels of UHRF1 in cancer cells leads to TSG silencing and DNA repair inhibition, thus contributing to tumor progression through the regulation of DNA and histone methylation." (PMID 36060265, 2022). "UHRF1 has been demonstrated to induce chemoresistance and radioresistance in several cancers, including PCa 35-37." (PMID 35517427, 2022).
cancer (continued). "Several studies have shown that TQ can decrease UHRF1 expression in cancer cells with the subsequent induction of apoptosis." (PMID 35566130, 2022). "UHRF1 is carcinogenic in humans, and the expression of UHRF1 is negatively correlated with the survival time of cancer patients." (PMID 35656341, 2022). "Knocking down of UHRF1, which is upregulated in several types of cancer, induces changes in the AS events of two cancer cell lines." (PMID 35158828, 2022). "Throughout cancer development, the main published downstream targets of UHRF1 were tumor suppressor genes." (PMID 35996525, 2022). "In another study, the knockdown of UHRF1 in HCT116 cancer cells induced cell cycle arrest in G2/M and promoted caspase-8 dependent apoptosis." (PMID 36077796, 2022). "From this, 15 genes were found to be essential in all TNBC cell lines including some of the well-known regulators of cancer cell fitness, such as UHRF1, PELP1 and PRMT1." (PMID 35973998, 2022). "Although an increasing number of investigations have begun to decode functional roles of UHRF1 in cancer biology 15, 16, few studies are focused on tumor UHRF1's interactions with immune cells, such as TAMs." (PMID 35664070, 2022). "Liver tumor microenvironment is characterized by high-level expression of immunosuppressive factors including COX-2 and its product 39, PGE2, which induced UHRF1 expression and thereby promotes cancer growth." (PMID 35664070, 2022). "Emerging reports link UHRF1 overexpression in cancer with proliferation, migration/invasion, or both." (PMID 36068209, 2022). "This study identified UHRF1-induced activation of c-Jun/AP-1 and UHRF1-promoted transcription of inflammation/metastasis-related cytokines, which favored cancer cell migration and invasion." (PMID 35996525, 2022). "Numerous studies have reported that UHRF1 is highly overexpressed in many cancer types including bladder, lung and colorectal carcinomas." (PMID 36060265, 2022). "Consistently, fewer number of UHRF1 positive cancer cells were observed in the celecoxib-treated tumors." (PMID 35664070, 2022). "Experiments showed that cancer cells depleted of UHRF1 would activate the DNA damage response pathway, resulting in cell cycle stagnation in G2M and apoptosis dependent on the caspase-8 pathway." (PMID 35656341, 2022). "Recent evidence shows that at least in cancer cell lines, UHRF1 is regulated by the ERK pathway at the transcriptional level rather than by the proteasome." (PMID 35324392, 2022). "It is important that UHRF1, as part of DNA methylation and histone modification of key regulatory factor, plays an important role in the occurrence of cancer." (PMID 35656341, 2022). "Previously, it has been shown that targeting the SRA domain of UHRF1 with various natural compounds provide a promising strategy for chemotherapeutic purpose in cancer cell lines." (PMID 35991572, 2022). "For example, large-scale cancer genomic data analyses revealed that lung adenocarcinoma or acute myeloid leukemia patients with a high expression level of UHRF1 had significantly worse survival outcomes." (PMID 35996525, 2022). "Given its role in cancer, UHRF1 is an attractive therapeutic target, but efforts to develop chemical modulators have met with limited success." (PMID 33441849, 2021). "UHRF1 targeted therapy sensitizes cancer cells to chemotherapeutic drugs by augmenting oxidative stress-mediated apoptosis." (PMID 33658396, 2021). "Inhibiting UHRF1 reverses the cancer cell epigenetic code as a whole (DNA methylation and the histone code) and leads to reactivation of TSGs." (PMID 33922029, 2021). "UHRF1 plays important yet complicated roles in cancer development and numerous studies have indicated that its silencing boosts tumor suppressor gene expression, causes cell cycle arrest, and triggers cancer cell apoptosis." (PMID 33441849, 2021). "UHRF1 is overexpressed in cancers, where it inhibits the expression of many tumor suppressor genes, including BRCA1, P16 and P2120–25." (PMID 33441849, 2021).